MUC1 (mucin 1, cell surface associated)
Diseases named in the same sentence as MUC1 in open-access papers (continued):
Sharing a sentence is not in itself a finding about the gene and the disease.
liver cancer (18 papers, 2011 to 2025). An epithelial or non-epithelial malignant neoplasm that arises from the liver. "Other studies have investigated the diagnostic and prognostic significance of serum MUC1 levels in liver cancers." (PMID 36980526, 2023). "In addition, in another cohort of liver cancer patients, we found that MUC1 was associated with CD8+T cell activation and function using flow cytometry." (PMID 36738352, 2023). "We identified YWHAE as significantly associated with liver fibrosis, AVIL, FIS1, MUC1, ACOT7, CLUH, HNF4A, and TNFSF10 with liver cancer, and AVIL with liver disease-related mortality (FDR-adjusted P values < 0.05)." (PMID 38862964, 2024). "Specifically, MUC1 has been reported to be highly expressed in various epithelial adenocarcinomas, including ovarian, breast, lung and liver cancers." (PMID 38517922, 2024). "In paired primary liver cancer and lung metastatic tumor tissues from the same patient, we observed higher MUC1 protein levels in lung metastases than in primary liver cancer." (PMID 36738352, 2023). "For instance, MUC1 has been reported to be expressed during liver cancer progression, and the genetic knockdown or antibody-mediated targeting of MUC1 has been shown to inhibit its tumor-promoting functions in HCC." (PMID 36980526, 2023). "miR-485-5p is associated with inflammation and immune responses, and it upregulates MUC1 to promote liver cancer progression." (PMID 38115130, 2023). "We previously reported that peanut agglutinin (PNA)-conjugated liposomes showed enhanced drug delivery efficiency to MUC1-positive liver cancer cells." (PMID 35784721, 2022). "Studies have found that MUC1 is a key target of SM to inhibit the growth of liver cancer, and that SM can inhibit the growth of liver cancer cells by up-regulating the expression of miR-4726-5p and binding to the MUC1 protein." (PMID 36278230, 2022). "Although TGF-β signaling has been considered a therapeutic target in cancers, our present results demonstrate that MUC1 is an attractive target in liver cancer therapy." (PMID 26057631, 2015). "Over-expression of MUC1 is associated with invasive and metastatic colon cancer, and MUC1 is also expressed on liver cancers." (PMID 21283832, 2011). "In paired primary liver cancer and lung metastatic tumor tissues from the same patient, we observed higher MUC1 protein levels in lung metastases than in primary liver cancer, and MUC1 was negatively correlated with CD8+T and Treg cells in the metastatic TME and positively correlated with DC." (PMID 36738352, 2023). "Immunohistochemistry detected MUC1 in normal liver, liver cancer, and lung metastases." (PMID 36738352, 2023). "According to these results, abnormally high expression level of MUC1 in liver cancer cells may inhibit the function of CD8+TILs through the high expression of PDL1, forming an inhibitory immune microenvironment, resulting in metastasis of cancer cells." (PMID 36738352, 2023). "Using immunofluorescence staining of paired primary liver cancer and lung metastatic tumor tissues from the same patient, we found that MUC1 expression was negatively correlated with CD8+T and Treg cells in the metastatic TME and positively correlated with DC cells." (PMID 36738352, 2023). "We also found that patients with high MUC1 expression levels were more likely to develop lung metastases and that MUC1 expression levels were significantly higher in lung metastases than in primary liver cancer." (PMID 36738352, 2023). "In addition, we found that MUC1 was associated with CD8+T cell activation and function using flow cytometry in another cohort of patients with liver cancer." (PMID 36738352, 2023). "We also find increased expression of myofibroblasts and fibrosis markers (PDGFRB, COL1A1, COL3A1, COL11A1) and early liver cancer markers (GPC3 and MUC1)." (PMID 41065540, 2025).
liver cancer (continued). "A phase I/II clinical trial (NCT02839954) is underway to evaluate the safety and effectiveness of anti‐MUC‐1 CAR‐pNK cells in MUC‐1 positive refractory solid tumours, including liver cancer." (PMID 34423899, 2021). "When the MUC1/KL-6 levels in sera from various liver cancer patients were compared, significantly higher levels were noted in CC patients than in HCC, metastatic and healthy individuals." (PMID 30875782, 2019). "However, the effects of MUC1 on the liver cancer lung metastasis have not yet been investigated." (PMID 36738352, 2023).
pneumonia (18 papers, 2009 to 2025). An acute, acute and chronic, or chronic inflammation focally or diffusely affecting the lung parenchyma, caused by an infection in one or both of the lungs (by bacteria, viruses, fungi, or mycoplasma.). "Five clinical strains of Pa isolated from blood cultures of pneumonia patients stimulated MUC1-ED shedding comparable with the PA01 and PAK laboratory strains." (PMID 34811449, 2021). "Accordingly, we determined serum levels of sRAGE, CC16, SP-D, CYFRA21-1, and KL-6/MUC1 in polytraumatized patients with severe chest trauma at risk for developing ARDS and/or pneumonia at admission and on the second day after the trauma occurred." (PMID 28380043, 2017). "Measurement of MUC1-ED and flagellin BALF levels offer a rapid, reliable means to identify ventilated patients with Pa pneumonia that might serve as a guide for empiric antibiotic therapy." (PMID 34811449, 2021).
acute myeloid leukemia (17 papers, 2012 to 2025). Acute myeloid leukemia (AML) is a group of neoplasms arising from precursor cells committed to the myeloid cell-line differentiation. "Recently, the adverse prognostic effect of MUC1 expression has been reported in acute myeloid leukemia (AML)." (PMID 40179083, 2025). "Phase 1/2 clinical trial results demonstrate efficacy for GO-203-2C, a peptide that blocks MUC1 dimerization, in combination therapy with decitabine in acute myeloid leukemia (AML) patients." (PMID 37720348, 2023). "Lack of miR-200c significantly increased the expressions of PD-L1 and MUC1 oncoprotein in acute myeloid leukemia, which showed that miR-200c was one of the critical negative regulators of PD-L1." (PMID 32922506, 2020). "In the same way, MUC1, an oncoprotein aberrantly expressed in acute myeloid leukemia (AML) cells, regulates ROS levels and the differentiation of hematopoietic cells." (PMID 22175013, 2012). "In this case, specifically, the oncoprotein mucin-1 (MUC1), when silenced, led to an increase in the level of these miRNAs, which in turn suppressed the expression of PD-L1 in acute myeloid leukemia (AML)." (PMID 29949872, 2018). "In addition, MUC1 expression can be detected within certain hematopoietic malignancies, including myeloma and acute myeloid leukemia (AML)." (PMID 35883508, 2022). "Acute myeloid leukemia (AML) EVs are taken-up myeloid progenitor cells and thereby induce proliferation in the target MDSC population through the high expression of c-myc drived by MUC1 oncoprotein." (PMID 35003065, 2021). "Although the applicability of CD19-directed CAR-T therapy in acute myeloid leukemia (AML) is limited, alternative leukemic cell-specific antigens such as CD33, CD38, CD56, CD117, CD123, Lewis-Y, and Muc-1 are currently being explored." (PMID 34203935, 2021).
autosomal dominant tubulointerstitial kidney disease (17 papers, 2016 to 2025). "It is noteworthy that in autosomal dominant tubulointerstitial kidney disease, renal failure is also associated with aberrant MUC1 expression." (PMID 34448730, 2021). "It shares some common features with autosomal dominant tubulointerstitial kidney diseases caused by mutations in MUC1 (mucin 1, 1q21), HNF1B (HNF1beta, 17q12), REN (renin, 1q32) and SEC61A1 (Sec 61 translocon alpha 1 subunit, 3q21)." (PMID 28437467, 2017). "Deleterious germline mutations in the MUC1 gene is a well-documented cause of medullary cystic kidney disease, also known as mucin-1 kidney disease." (PMID 28241424, 2017). "That mistakes can occur here is amply demonstrated by the recent report on a mutation within the MUC1 tandem repeat which results in medullary cystic kidney disease 1 (MCKD1)." (PMID 27768738, 2016). "For instance, MUC1 mutations directly cause autosomal dominant tubulointerstitial kidney disease." (PMID 34327857, 2021). "Heterozygous variants in the calcium-sensing receptor gene CASR (pLI = 0.05) can cause hypocalciuric hypercalcemia while autosomal-dominant tubulointerstitial kidney disease can be caused by variants in UMOD (pLI = 0), MUC1 (pLI = 0.02) or REN (pLI = 0)." (PMID 39099563, 2024). "Autosomal dominant tubulointerstitial kidney disease (ADTKD) is an important hereditary kidney disease, mainly caused by mutations of uromodulin (UMOD) or mucin-1 (MUC-1)." (PMID 36431026, 2022). "Medullary cystic kidney disease (recently named tubulointerstitial kidney disease TKD), caused by mutations in MUC1 and UMOD, is considered the autosomal dominant NPHP, with a later onset than the recessive form." (PMID 34204582, 2021). "Additional studies focused on MUC1 (a gene responsible for medullary cystic kidney disease (MCKD) type 1) reveal that renal expression of alternatively spliced mRNA isoform of MUC1 may be the key biological mechanism behind the genetic association signal captured in previous GWAS of CKD-dt." (PMID 30467309, 2018).
cervical carcinoma (17 papers, 2005 to 2025). A carcinoma arising from either the exocervical squamous epithelium or the endocervical glandular epithelium. "The association of MUC1-EGFR-IL-6 with poor disease-free survival in cervical cancer patients with chemotherapy was also found from TCGA data mining." (PMID 31772161, 2019). "Consistent with published work, we found that increased MUC1 expression in cervical cancer cells was associated with increased phosphorylation and total level of EGFR." (PMID 28796259, 2017). "Immunohistochemistry (IHC) and cell immunofluorescence confirmed increased MUC1 expression in cervical cancer tissues and cell lines." (PMID 41418390, 2025). "Taken together, these data confirm that MUC1 secreted by tumor cells interacts with SIGLEC9 on CD4+ T-cells in the tumor microenvironment of cervical cancer." (PMID 41418390, 2025). "Further Western blot analysis indicated that MUC1 was required for ERK phosphorylation in cervical cancer cells." (PMID 38702644, 2024). "Transwell assays showed that MUC1 knockout significantly decreased the migration and invasion of cervical cancer cells." (PMID 38702644, 2024). "In the squamous type of cervical cancer, MUC1 is more highly expressed in metastatic tumoral cervical tissues than in negative lymph nodes." (PMID 38702644, 2024). "Research has also indicated that MUC1 can induce chemoresistance, especially by promoting the accumulation of cancer stem cells in cervical cancer." (PMID 38361923, 2024). "Elevation of miR-512-5p contributes to the reduction of radioresistance in cervical cancer cells by inhibiting MUC1 expression." (PMID 32662743, 2020). "Collectively, the data from cancer patients are in line with the notion that activation of MUC1-EGFR-IL-6 signaling correlated with poor outcome of cervical cancer patients with chemotherapy." (PMID 31772161, 2019). "To examine the clinical relevance of the MUC1-EGFR-IL-6 axis in cancer patients, we collected 20 paired pre- and post-NACT tumor specimens from cervical cancer patients and performed immunohistochemistry to detect the expression of MUC1, EGFR, and IL-6." (PMID 31772161, 2019). "Mining TCGA data sets also uncovered the expressions of MUC1-EGFR-IL-6 correlates with poor disease-free survival in chemo-treated cervical cancer patients." (PMID 31772161, 2019). "Given the association of MUC1 with chemoresistance, we made an attempt to investigate a potential involvement of MUC1 in chemoresistance in cervical cancer and pulmonary mucoepidermoid lung carcinoma (PMC)." (PMID 28796259, 2017). "Our studies revealed high MUC1 levels in endometrial adenocarcinomas and cervical carcinomas when compared to the normal endometrial and cervical tissues." (PMID 16188033, 2005). "Moreover, SIGLEC9 is expressed on TAMs and T-cells, where it interacts with MUC1 secreted by cervical cancer cells, facilitating immune evasion." (PMID 41418390, 2025). "In cervical cancer, MUC1 is involved in the malignancy of cervical adenocarcinoma." (PMID 38702644, 2024). "In cervical cancer, MUC1, MUC4 and MUC20 were reported to be overexpressed in the squamous type." (PMID 38702644, 2024). "Similarly, MUC1 induced the resistance of both lung and cervical cancer cell lines to paclitaxel by upregulating ABCB1 in an EGFR-dependent manner." (PMID 38254882, 2024). "Therefore, the implications and regulatory mechanism of MUC1 in cervical cancer need further exploration." (PMID 38702644, 2024). "Indeed, by using a loss-of-function approach, we confirmed that activation of the EGFR-IL-6 pathway and enrichment of paclitaxel-resistant CSCs depended on MUC1 expression in cervical cancer." (PMID 31772161, 2019). "In our cervical cancer xenograft mouse model, co-administration of PTX with EGFR inhibitor erlotinib significantly prevented the tumor growth and relapse, which was associated with reduced expression of MUC1 and ABCB1, and diminished activity of EGFR." (PMID 28796259, 2017).
cervical carcinoma (continued). "Therefore, the role of the MUC1/SIGLEC9 axis in cervical cancer deserves to be investigated." (PMID 41418390, 2025). "However, the function and regulatory mechanism of MUC1 in cervical cancer has rarely been studied." (PMID 38702644, 2024). "A phase I/II study (NCT03356795) evaluates the safety and efficacy of CAR T cells in cervical cancer patients whose tumour cells express TAAs such as GD2, PSMA, Muc1 or mesothelin." (PMID 33205441, 2021). "More importantly, positive correlations between the expressions of MUC1, EGFR, and IL-6 were found in 20 cervical cancer patients after chemotherapy." (PMID 31772161, 2019). "Apart from both in vitro and in vivo data supporting a critical role of EGFR in MUC1-mediated paclitaxel-resistance, our clinical study showed elevated expression of MUC1, EGFR, and IL-6 in post-chemotherapy cervical cancer tissues." (PMID 31772161, 2019). "The study indicates that MUC1, secreted by cervical cancer cells, interacts with SIGLEC9 on macrophages and T-cells, promoting TAMs differentiation and inhibiting T-cell function, ultimately contributing to immune evasion in cervical cancer." (PMID 41418390, 2025). "MUC1 could upregulate ITGA2 and ITGA3 expression via ERK phosphorylation, promoting the proliferation and metastasis of cervical cancer cells." (PMID 38702644, 2024). "MUC1 was overexpressed in CSCC, activating the phosphorylation of ERK, which enhanced the expression of ITGA2 and ITGA3, thereby promoting the malignant progression of cervical cancer cells." (PMID 38702644, 2024). "We found that the expression of MUC1 increased from non-neoplastic glandular lesions of the cervix to cervical cancer, which was similar to the findings of other studies." (PMID 38702644, 2024). "Collectively, our work has demonstrated that the MUC1-EGFR-CREB/GRβ axis stimulates IL-6 expression to induce CSCs enrichment and importantly, this effect can be abrogated by erlotinib, uncovering a novel strategy to treat paclitaxel-resistant cervical cancer." (PMID 31772161, 2019). "Levels of expression of MUC1 in cervical carcinomas were significantly different from normal cervical tissue." (PMID 16188033, 2005).
esophageal cancer (17 papers, 2013 to 2025). A primary or metastatic malignant neoplasm involving the esophagus. "The high-expression of MUC1 is associated with a poor prognosis for esophageal cancer patients, contributes to SCC metastasis, and plays a pivotal role in the progression to AC." (PMID 35664298, 2022). "The experimental results showed that the enhanced MUC1-CAR-T cells had significant anti-tumor effects on esophageal cancer cells, together with more sustained tumor killing and proliferative capacity compared with conventional MUC1-CAR-T cells." (PMID 38919533, 2024). "Current clinical trials, evaluate anti-MUC1 CAR T cells with PD-1 knockout in advanced esophageal cancer (NCT03706326) and anti-EGFR CAR T cells with TGFBR2 knockout in EGFR-positive solid tumors (NCT04976218)." (PMID 38962014, 2024). "MUC1 is a 200 kDa complex glycoprotein with both transmembrane and secreted isoforms, and is highly expressed in various malignant tumors including esophageal cancer." (PMID 38919533, 2024). "Previous studies have confirmed that MUC1 is aberrantly overexpressed in thoracic malignancies, including lung cancer, breast cancer, and esophageal cancer, and serves as an oncogene in the tumorigenesis of various human adenocarcinomas." (PMID 35911706, 2022). "MUC1 is a glycoprotein whose expression levels are aberrantly upregulated in various carcinomas, such as esophageal cancer." (PMID 34858843, 2021). "Currently, the potential targets against esophageal cancer include MUC1, HER2, EpCAM, EpA2 and CD276, for CAR-T cell therapy, NY-ESO-1, MAGE-A3 and MAGE-A4 for TCR-T cell therapy." (PMID 34858843, 2021). "For instance, MUC1, which is overexpressed in the colon, breast, lung, pancreatic, bladder, ovarian, bladder, gastric, and esophageal cancer, has been reported as a critical protein for the development of pluripotency, platform proteins secreted by tumor-associated surface proteases." (PMID 40699805, 2025). "To date, the exploration of CAR-T cells therapy in esophageal cancer has been limited, with only EphA2, HER2, MUC1, and CD276 being identified as potential therapeutic targets in preclinical studies." (PMID 40510363, 2025). "A recent report describes the design of a CAR-T cell that both targets MUC1 and activates cytokine-cytokine signaling, and verified the effect of this enhanced CAR-T cell therapy on esophageal cancer." (PMID 38919533, 2024). "In summary, these data indicate correlation between the proproliferation and antiapoptotic effects of MUC13 with the expression of GLANT14, MUC3A, MUC1, MUC12 and MUC4 in esophageal cancer." (PMID 37395858, 2023). "This enhanced MUC1-CAR-T cell has stronger cytotoxicity and more significant inhibitory effect on esophageal cancer (EC)." (PMID 37894512, 2023). "In esophageal cancer, miR-1291 can target the seed region of the 3′ UTR of MUC1 to suppress MUC1-C expression." (PMID 35154471, 2022). "Esophageal cancer: This trial was completed on nine patients with advanced (stage IIIB/IV) esophageal cancer, four patients receiving a single and five receiving multiple doses of CAR T cells targeting MUC1 with PD-1 KO." (PMID 41354926, 2025). "It has been found in the study of esophageal cancer, another epithelial cell carcinoma that the expression level of C1GALT1 was positively correlated with MUC1 O- glycosylation, and the co expression of MUC1 and C1GALT1 was negatively correlated with survival rate." (PMID 38699634, 2024). "In this study, we confirmed that GLANT14, MUC3A, MUC1, MUC12, and MUC4 regulatory factors which related to the O-glycan process were overexpressed and downregulated with MUC13 knockdown in esophageal cancer cells, resulting in insufficient tumor growth and proliferation." (PMID 37395858, 2023).
esophageal cancer (continued). "Another study reported that MUC1-targeted CAR-T cells reduced the proliferation capability of esophageal cancer cells by activating the JAK/STAT pathway and inhibited tumor growth in transplantation models and patient-derived tumor xenograft (PDX) models of esophageal cancer in vivo." (PMID 35911706, 2022). "The engineered MUC1 targeted CAR-T cells activated the JAK-STAT pathway, secreted higher level of cytokines, showed superior proliferative capacity and persistence, and mediated greater antitumor activity both in subcutaneous xenograft tumors and a PDX mouse model of esophageal cancer." (PMID 34858843, 2021).